ATP6V0D1 (ATPase H+ transporting V0 subunit d1)
Description:
Subunit of the V0 complex of vacuolar(H+)-ATPase (V-ATPase), a multisubunit enzyme composed of a peripheral complex (V1) that hydrolyzes ATP and a membrane integral complex (V0) that translocates protons. V-ATPase is responsible for acidifying and maintaining the pH of intracellular compartments and in some cell types, is targeted to the plasma membrane, where it promotes acidification of the extracellular environment. The V-ATPase complex also acts as an activator for mTORC1 on lysosomal membrane by promoting the guanine nucleotide exchange factor (GEF) of the Ragulator complex, thereby enabling mTORC1 recruitment. May play a role in coupling of proton transport and ATP hydrolysis (By similarity). In aerobic conditions, involved in intracellular iron homeostasis, thus triggering the activity of Fe(2+) prolyl hydroxylase (PHD) enzymes, and leading to HIF1A hydroxylation and subsequent proteasomal degradation. May play a role in cilium biogenesis through regulation of the transport and the localization of proteins to the cilium (By similarity).
Synonyms: p39; ATP6D; VPATPD; ATP6DV; VATX; Vma6
Tractability: Small molecule: a structure with a bound ligand is known. Antibody: UniProt places it where antibodies can reach, with high confidence; its Gene Ontology location is reachable by antibodies, with medium confidence. PROTAC: ubiquitination databases record sites on it; its protein half-life has been measured.
Gene: Protein-coding gene on chromosome 16 (67,438,005 to 67,481,188, reverse strand). Ensembl gene ENSG00000159720.
Subcellular location: Membrane; Lysosome membrane; Cytoplasmic vesicle, clathrin-coated vesicle membrane
Pathways (Reactome):
Cellular responses to stimuli: Amino acids regulate mTORC1; XBP1(S) activates chaperone genes
Transport of small molecules: Ion channel transport; Transferrin endocytosis and recycling
Developmental Biology: Regulation of MITF-M-dependent genes involved in lysosome biogenesis and autophagy
Immune System: ROS and RNS production in phagocytes
Signal Transduction: Insulin receptor recycling
Gene Ontology:
Molecular function: guanyl nucleotide exchange factor activator activity; protein binding; proton-transporting ATPase activity, rotational mechanism; proton transmembrane transporter activity
Biological process: cellular response to amino acid stimulus; cellular response to increased oxygen levels; intracellular iron ion homeostasis; positive regulation of TORC1 signaling; cilium assembly; proton transmembrane transport; regulation of macroautophagy; vacuolar acidification; vacuolar transport; homeostatic process; synaptic vesicle lumen acidification
Cellular component: centrosome; extracellular exosome; lysosomal membrane; lysosomal proton-transporting V-type ATPase complex; membrane; vacuolar proton-transporting V-type ATPase complex; early endosome; endosome membrane; phagocytic vesicle membrane; plasma membrane proton-transporting V-type ATPase complex; vacuolar proton-transporting V-type ATPase, V0 domain; clathrin-coated vesicle membrane; presynapse; proton-transporting V-type ATPase complex; proton-transporting V-type ATPase, V0 domain
Genetic constraint (gnomAD): Loss-of-function variants: 13 observed, 40.26 expected, observed/expected ratio (o/e) 0.32, 90% interval 0.21 to 0.51. The upper end of that interval is the gene's LOEUF score, 0.51, which puts it in group 2 of 6, group 1 being the genes least tolerant of losing a copy. Missense variants: 272 observed, 494.34 expected, observed/expected ratio (o/e) 0.55, 90% interval 0.5 to 0.61. Synonymous variants: 191 observed, 201.12 expected, observed/expected ratio (o/e) 0.95, 90% interval 0.84 to 1.07.
Homologues: Orthologues: chimpanzee ATP6V0D1 (100% identical), guinea pig ATP6V0D1 (100% identical), macaque ATP6V0D1 (100% identical), pig ATP6V0D1 (100% identical), rabbit ATP6V0D1 (100% identical), mouse Atp6v0d1 (99% identical), rat Atp6v0d1 (99% identical), dog ATP6V0D1 (99% identical), tropical clawed frog atp6v0d1 (95% identical), zebrafish atp6v0d1 (94% identical), Caenorhabditis elegans vha-16 (74% identical), Drosophila melanogaster VhaAC39-2 (44% identical). Paralogues in human: ATP6V0D2 (68% identical).
Diseases named in the same sentence as ATP6V0D1 in open-access papers:
ATP6V0D1 is named in the same sentence as 34 diseases in open-access papers, as found by Europe PMC text mining. Sharing a sentence is not in itself a finding about the gene and the disease. The quoted sentences say what the papers report.
melanoma (3 papers, 2023 to 2025). A malignant, usually aggressive tumor composed of atypical, neoplastic melanocytes. "ATP6V0D1, which encodes a subunit of the proton pump involved in endocytic pathways, was identified as a risk factor for melanoma survival." (PMID 39439891, 2024). "SHAP value analysis ranked RPL35, KHDRBS3, ATP6V0D1, and CRIP2 as the most important contributors to melanoma classification." (PMID 40909289, 2025). "Previous studies also supported our result that ATP6V0D1 was widely expressed, while D2 was mainly expressed on the cell surface of human kidneys and osteoclasts; ATP6V0D2 is also overexpressed in most cancer tissues such as in melanoma, pancreatic cancer, and kidney cancer." (PMID 36980869, 2023).
pancreatic ductal adenocarcinoma (3 papers, 2023 to 2025). An infiltrating adenocarcinoma that arises from the epithelial cells of the pancreas. "This study aimed to investigate how ATP6V0D1 deficiency reshapes oncogenic signaling networks and cellular heterogeneity in pancreatic ductal adenocarcinoma (PDAC), while evaluating therapeutic strategies that exploit alkaliptosis-related vulnerabilities." (PMID 41019981, 2025). "Clinically, a high expression of ATP6V0D1 was correlated with prolonged survival of patients with pancreatic ductal adenocarcinoma." (PMID 37759668, 2023).
osteosarcoma (2 papers, 2022 to 2024). A usually aggressive malignant bone-forming mesenchymal neoplasm, predominantly affecting adolescents and young adults. "In this research, five oxidative phosphorylation genes linked to the prognosis of individuals with osteosarcoma were screened out, including ATP6V0D1, LHPP, COX6A2, MTHFD2, and NDUFB9." (PMID 38506898, 2024). "Finally, based on the results of previous screening, four UPRRGs (STC2, PREB, TSPYL2, and ATP6V0D1) were identified to establish a risk model for osteosarcoma via the multivariate Cox regression analysis." (PMID 35754801, 2022). "Finally, four genes (STC2, PREB, TSPYL2, and ATP6V0D1) were screened to construct and validate a risk signature to predict the prognosis of patients with osteosarcoma." (PMID 35754801, 2022). "The findings from the current research align with the results of two prior studies, both of which have demonstrated that ATP6V0D1 is a protective gene for osteosarcoma." (PMID 38506898, 2024). "On the other hand, ATP6V0D1 and LHPP were negatively correlated with risk scores, which suggested that they are protective genes for the clinical prognosis of patients with osteosarcoma." (PMID 38506898, 2024). "Next, to assess the role of UPRRGs in predicting the prognosis of osteosarcoma, we constructed a prognostic signature to predict the survival of osteosarcoma patients via four genes (STC2, PREB, TSPYL2, and ATP6V0D1)." (PMID 35754801, 2022). "The current investigation found no molecular biology studies related to ATP6V0D1 and osteosarcoma cells, suggesting that ATP6V0D1 may be a new research direction." (PMID 38506898, 2024).
Werner syndrome (2 papers, 2023). "Importantly, we identified ATP6V0D1 and RTN4 as novel markers that are frequently upregulated in sEVs from senescent and progeria cells derived from patients with Werner syndrome." (PMID 36768745, 2023). "Recently, novel senescent markers, ATP6V0D1 and RTN4, were shown to be increased in cells derived from patients with Werner syndrome, raising a possibility that they may serve as markers of disease progression." (PMID 37130431, 2023).
cardiomyopathy (1 paper, 2024). A disease of the heart muscle or myocardium proper. "We have identified vacuolar H+-ATPase subunit Vod1, encoded by Atp6v0d1, as a master regulator of adipogenesis, and adipose-specific deletion of Atp6v0d1 (Atp6v0d1AKO) in mice caused generalized lipodystrophy and spontaneous cardiomyopathy." (PMID 38505620, 2024).
dysferlinopathy (1 paper, 2023). "Analysis of muscle transcripts from patients with dysferlinopathy helped identify the following 7 upregulated DEGs involved in the cellular response to stress: HSPA9, RPTOR, MTOR, LAMTOR1, LAMTOR5, ATP6V0D1, and ATP6V0B." (PMID 38125829, 2023).
lysosomal disorders (1 paper, 2023). "Here, we found that lysosomal channel proteins (ATP6V0B, ATP6V1E1, ATP6V0D1, ATP6V1F) were significantly decreased in AD, which may mediate the elevation of lysosomal pH leading to lysosomal disorders." (PMID 37334737, 2023).
neuroblastoma (1 paper, 2025). Neuroblastoma (NB) is the most common solid, extracranial childhood tumor. "Our findings underscore the importance of ATP6V0D1 in neuroblastoma and suggest potential therapeutic strategies targeting V-ATPase for overcoming drug resistance." (PMID 40552114, 2025). "Overexpression of the ATP6V0D1 subunit of V-ATPase, previously reported in various cancers, was also observed in ellipticine-resistant neuroblastoma cells in our study." (PMID 40552114, 2025). "Knockdown of ATP6V0D1, but not ATP6V1H, enhanced ellipticine sensitivity, suppressed proliferation and migration, decreased lysosomal uptake, and induced G2/M arrest in neuroblastoma cell lines." (PMID 40552114, 2025).
Obesity (1 paper, 2024). Accumulation of substantial excess body fat. "Moreover, analysis of adipose tissues from diet-induced-obesity mice revealed a marked increase in ATP6V0D1 abundance, suggesting Vod1 subunit is involved in maintaining adipose homeostasis." (PMID 38505620, 2024).
Parkinson disease (1 paper, 2021). A progressive degenerative disorder of the central nervous system characterized by loss of dopamine producing neurons in the substantia nigra and the presence of Lewy bodies in the substantia nigra and locus coeruleus. "In Parkinson’s disease miR-5701 was reported to modulate mitochondrial-lysosomal cross talk, targeting genes involved in lysosomal biogenesis and mitochondrial quality control (VCP, LAPTMA4A, ATP6V0D1)." (PMID 34827683, 2021).
sarcoidosis (1 paper, 2022). Sarcoidosis is a multisystemic disorder of unknown cause characterized by the formation of immune granulomas in involved organs. "However, some UIC STAR cohort key determinant genes, such as ATP6V0D1, FTH1, G6PD, HCK, and SPI1 have been previously associated with sarcoidosis in other studies." (PMID 36311769, 2022).
tuberculosis (1 paper, 2022). A chronic, recurrent infection caused by the bacterium Mycobacterium tuberculosis. "ATPase H+ transporters, including ATP6AP1, ATP6V0B, and ATP6V0D1, were identified in the other module-related pathways such as lysosome, tuberculosis, and phagosome." (PMID 36034872, 2022).
ZIKV infection (1 paper, 2022). "ZIKV infection significantly upregulated genes related to lysosomal biosynthesis, including LAMP1 and CLCN7 (lysosomal transmembrane proteins); CSTB and CSTD (lysosomal hydrolases); and ATP6V1C1 and ATP6V0D1 (v-ATPase proteins)." (PMID 36405969, 2022).
cancer (6 papers, 2020 to 2025). A tumor composed of atypical neoplastic, often pleomorphic cells that invade other tissues. "As encoding a protein crucial in forming vacuolar ATPase (V-ATPase), V-type proton ATPase subunit d1 (ATP6V0D1) has been implicated in various cancer hallmarks, particularly invasion and metastasis." (PMID 38632516, 2024). "ATP6V0D1 (V-type proton ATPase subunit d1) acidifies various intracellular compartments in cancer cells and generates transport process energy." (PMID 32581649, 2020). "The V-ATPase H+ transporting genes (ATP6V0D1, ATP6V0C, ATP6V0E1) maintain the intracellular pH and thus are critical for the Warburg effect observed in the cancer cells." (PMID 38114687, 2023). "Similar to RNA-seq and qRT-PCR data, immunoblot analysis further confirmed the upregulation of ATP6V0D1 and ATP6V1B2 in cells cultured in suspension compared to the attached cancer cells." (PMID 34234852, 2021). "Importantly, blocking STAT3 signaling in cancer cells inhibited the expression of two members of the V-ATPase family - ATP6V1B2 and ATP6V0D1." (PMID 34234852, 2021).
tumor (3 papers, 2020 to 2024). "For instance, ATP6V0D1 shows significant upregulation in patients with advanced tumor stages, while TRIM27 is notably associated with worse overall survival outcomes." (PMID 39439891, 2024). "In this research, we revealed elevated ATP6V0D1 expression in both metastatic and tumour samples compared to normal ones." (PMID 38632516, 2024). "Furthermore, expression levels of biomarkers revealed higher ATP6V0D1 expression in both metastatic and tumour samples, while HDAC6 expression was higher in normal as well as metastatic samples." (PMID 38632516, 2024). "Therefore, the ATP6V0D1 may react actively as a protective factor inhibiting tumour growth and progression through disruption of pH homeostasis, suggesting a possible defending mechanism against tumour." (PMID 38632516, 2024).
infection (1 paper, 2024). The state of being infected such as from the introduction of a foreign agent such as serum, vaccine, antigenic substance or organism. "Infection of these gRNA-expressing A549-AC lines with SARS-CoV-2 at various MOI conditions produced consistent phenotypes: (i) knocking out pro-viral ATP6V0D1 or DPAGT1 increased cell viability and (ii) knocking out anti-viral DAZAP2, VTA1, or KLF5 decreased cell viability." (PMID 38168026, 2024).
ATP6V0D1 also shares sentences with these, for which no sentence is quoted: breast carcinoma (2 papers); pancreatic cancer (2); cardiac hypertrophy (1); chronic kidney disease (1); colon cancer (1); COVID-19 (1); diabetes (1); endometrial cancer (1); generalized lipodystrophy (1); Hypercholesterolemia (1); Hypertension (1); Insulin resistance (1); kidney cancer (1); lipodystrophy (1); liver cancer (1); progeria (1); renal carcinoma (1); thyroid cancer (1).